OR8J3 (olfactory receptor family 8 subfamily J member 3)
Description:
Odorant receptor.
Synonyms: OR11-173
Tractability: Antibody: UniProt places it where antibodies can reach, with medium confidence; UniProt predicts a signal peptide or a membrane-spanning region; its Gene Ontology location is reachable by antibodies, with medium confidence.
Gene: Protein-coding gene on chromosome 11 (56,134,721 to 56,140,201, reverse strand). Ensembl gene ENSG00000167822.
Subcellular location: Cell membrane
Pathways (Reactome):
Sensory Perception: Expression and translocation of olfactory receptors
Gene Ontology:
Molecular function: olfactory receptor activity; G protein-coupled receptor activity
Biological process: G protein-coupled receptor signaling pathway; sensory perception of smell; detection of chemical stimulus involved in sensory perception of smell
Cellular component: plasma membrane; membrane
Genetic constraint (gnomAD): Missense variants: 409 observed, 381.56 expected, observed/expected ratio (o/e) 1.07, 90% interval 0.99 to 1.16. Synonymous variants: 165 observed, 144.36 expected, observed/expected ratio (o/e) 1.14, 90% interval 1.01 to 1.3.
Homologues: Orthologues: chimpanzee OR8J3 (99% identical), macaque OR8J3 (93% identical), mouse Or8j3 (84% identical), rat Or8j3 (83% identical), dog OR8J3 (80% identical). Paralogues in human: OR8J1 (89% identical), OR8J2 (78% identical), OR8K3 (57% identical), OR8K5 (56% identical), OR8U3 (56% identical), OR8U1 (55% identical), OR8K1 (53% identical), OR8G5 (51% identical), OR8G1 (51% identical), OR8B2 (50% identical), OR8B3 (50% identical), OR8A1 (50% identical), and 84 more.